TOX2 (TOX high mobility group box family member 2)
Diseases named in the same sentence as TOX2 in open-access papers (continued):
Sharing a sentence is not in itself a finding about the gene and the disease.
tumor (continued). "For instance, double KO of TOX1 and TOX2 exhibited superior tumor control in solid tumors." (PMID 40693464, 2025). "Moreover, the phosphatase PRL-3, which is associated with the spread of cancer cells, has been recognized as a crucial protein controlled by TOX2 in the regulation of tumor growth." (PMID 39838405, 2025). "Consistent with human CD8 GZMB+, the human-like CD8 GZMB+ clusters (Cluster0, 1) also had significantly higher Ctla4, Tox and Tox2 expression in the tumor environment injected with Macro CD5L+, while the expression of Pdcd1 (PD1) was not different between the two groups." (PMID 38245530, 2024). "However, TOX and TOX2-deleted CAR-expressing tumor-infiltrating T lymphocytes (TILs) are superior to TOX- or TOX2-deleted WT CAR TILs or CAR TILs in terms of clearing human CD19+ tumor cells." (PMID 36969216, 2023). "Silencing TOX2 also impaired tumor formation of NKTL cells in vivo." (PMID 37032358, 2023). "Indeed, we found that Tox and Tox2 directly control the transcriptional regulation of Pdcd1 and Lag3 expression, largely determining the functional incompetence of tumor-infiltrating CD4+ T cells from CD4/ALK4-KO mice." (PMID 34548096, 2021). "TOX2 is specifically expressed in the tumor-specific B cell subpopulation (B7) in CLL donor (44/369), but it is almost not expressed in the other two B cell subpopulations (5/522 and 0/535) in CLL donor, nor is it expressed in B cell subpopulation in the healthy donor (3/469)." (PMID 34362918, 2021). "To explore whether IRX2 and TOX2 may also have an impact on tumor prognosis, we performed a survival analysis using a web-tool called PROGgeneV2." (PMID 29568396, 2018). "Furthermore, we evaluated the expression levels of selected differentially methylated genes and identified two biomarkers, one, IRX2, related to the tumor localization and the other, TOX2, as tumoral biomarker." (PMID 29568396, 2018). "In studies on tumor-inoculated mice, it was shown that CAR-T cells deficient in both TOX and TOX2, or with triple KO of NR4A1, NR4A2, and NR4A3, had a greater anti-cancer activity and improved animal survival; therefore, targeting the TOX/NR4A axis may reduce the depletion of CAR-T cells in TME." (PMID 37296906, 2023). "Furthermore, the genome-wide impact of epigenetic inactivation assessed by siRNA revealed that TOX2 knockdown modulated multiple molecular pathways including important modulators of tumor microenvironment such as tissue remodeling, inflammatory response, and cell differentiation." (PMID 22496870, 2012). "Here, we observed two distinct TIM3 expression patterns (high & low) in T-ALL cell lines or tumor samples with high TOX and TOX2 levels based on a GEO public database analysis." (PMID 39080376, 2024). "Another study using a CAR T cell model demonstrated that TOX and TOX2 are necessary to impose CAR T exhaustion, which were highly induced in exhausted CAR+ tumor-infiltrating lymphocytes (CAR TILs)." (PMID 36761757, 2023). "TOX2 (TOX high-mobility group box family 2) is a transcriptional coactivator that modulates multiple pathways including tissue remodeling and tumor microenvironment functions." (PMID 36992820, 2023). "Recent studies have demonstrated that the mRNA expression of TOX2 and TOX3 is significantly elevated in tumor tissue from individuals with sCRC, suggesting a potential role for these molecules in the development and progression of the disease." (PMID 37835436, 2023). "Moreover, based on the finding that TOX expression was negatively correlated with the effects of PD-1 immunotherapy, it has been speculated that combined anti-TOX or anti-TOX2 and immune checkpoint inhibitor therapy may be a new approach for tumor immunotherapy." (PMID 33743809, 2021). "The analysis reveals a tumor-specific B cell subpopulation in the CLL patient and identifies TOX2 as a potential regulator of this subpopulation." (PMID 34362918, 2021).
tumor (continued). "Together, these data suggest that TOX, and potentially TIM-3, CTLA-4, VISTA, TIGIT, KLRG1, TOX2, SIRT1, Ki-67, and Helios mRNA levels in CRC tumor tissues increase in advanced disease stages, suggesting their possible roles in CRC progression." (PMID 32393998, 2020). "We also found that mRNA levels of TOX2 and TOX3 were significantly higher in CRC tumor tissues, suggesting their potential roles in CRC development and/or progression." (PMID 32393998, 2020). "We found that TOX and potentially TIM-3, CTLA-4, VISTA, TIGIT, KLRG1, TOX2, SIRT1, Ki-67, and Helios mRNA levels in tumor tissue were elevated in advanced disease stages, suggesting their potential roles in CRC progression." (PMID 32393998, 2020). "Simultaneous loss of TOX and TOX2 improves the antitumor potency of TILs, but loss of TOX2 alone is not sufficient to significantly reduce tumor burden, suggesting that, in mouse models, the contribution of TOX2 to exhaustion is weaker compared to TOX." (PMID 37467321, 2023). "Interestingly, we discovered that in tumor-infiltrating CD4+ T cells Tox and Tox2 bind on the genetic locus of NFAT2, suggesting the existence of a positive feedback loop in the regulation of gene expression between NFAT2 and Tox." (PMID 34548096, 2021). "CD4+ T cells genetically unresponsive to activin-A, failed to elicit effective anti-tumor properties and displayed an exhausted molecular signature governed by the transcription factors Tox and Tox2." (PMID 34548096, 2021). "Importantly, we observed that in lung tumor-infiltrating CD4+ T cells from CD4/ALK4-KO mice, Tox and Tox2 demonstrated significantly enriched binding on the -23 kb enhancer sequence of Pdcd1, compared to their WT counterparts." (PMID 34548096, 2021). "On the contrary, Tox and Tox2 did not bind on the genetic locus of Jun in tumor-infiltrating CD4+ T cells from CD4/ALK4-KO mice." (PMID 34548096, 2021). "Levels of TIM-3, CTLA-4, TIGIT, TOX, TOX2, and SIRT1 genes in tumor tissue were significantly higher than that of the circulation; their expressions within the TME could be induced by tumor-mediated immunosuppression." (PMID 32393998, 2020). "By this means, recently published data showed that downregulation of key proteins involved in T cells terminal differentiation and exhaustion such as NR4A, TOX/TOX2, TET2, Regnase1, or PTPN22 increased T cell-based treatment half-life and improve anti-tumor performance." (PMID 33287392, 2020). "Importantly, the expression of TOX, TOX2 and members of the NR4A family was highly induced in CD8+CAR+PD-1hi1TIM3+hi tumor-infiltrating lymphocytes (TILs) by the Cl/Cn-regulated nuclear factor of activated T cells (NFAT), even in the absence of activating protein-1, which is its partner protein." (PMID 36969216, 2023). "In the neoadjuvant context of ICBs, tumor-specific CD8+ T cells isolated from non-major pathological response patients expressed high levels of genes associated with T cell dysfunction, such as TOX2, CTLA-4, TIM-3, and CD39." (PMID 37881432, 2023). "It was demonstrated that TOX and TOX2 can cooperatively work together to induce T cell exhaustion by upregulating IC expression in chimeric antigen receptor (CAR) T cell model, and their targeting was shown to be beneficial in enhancing anti-tumor immune responses and reducing tumor growth." (PMID 32393998, 2020). "This may suggest that elevated expression of PD-1, TIM-3, CTLA-4, TIGIT, TOX, TOX2, and SIRT1 genes in the TME of CRC is induced by tumor-associated, factors, unlike VISTA, and LAG-3." (PMID 32393998, 2020). "Additionally, there are no studies on the expression of TOX2 and TOX3 in CRC tumor tissues." (PMID 32393998, 2020).
cancer (10 papers, 2012 to 2024). A tumor composed of atypical neoplastic, often pleomorphic cells that invade other tissues. "We use TOX2-SE as example to demonstrate that the discovery strategy of key SE-associated genes in the current study is a useful tool for uncovering novel, cancer-unique oncogenes." (PMID 37032358, 2023). "Taken together, the list of genes affected by TOX2 elimination play pivotal roles in drug resistance, cancer progression, metastasis, and worsen clinical outcomes." (PMID 37032358, 2023). "Our results thus suggest a role for human TOX2, in contrast to exhaustion regulator TOX, as a potentiator of central memory differentiation of CAR T cells, with plausible utility in CAR T cell cancer therapy via modulated TOX2 expression." (PMID 37467321, 2023). "Other important genes in this list downregulated by TOX2-shRNA, such as ITGB7, SLAMF1, CD244, DPYSL3, KRT80 and KRT7, have been implicated in cancer progression or drug resistance." (PMID 37032358, 2023). "Several elegant studies have revealed that Tox, and to a lesser extent Tox2, impose T cell exhaustion in the context of chronic infections and cancer." (PMID 34548096, 2021). "Extension of these assays to TOX, TOX3, and TOX4 genes that share similar genomic structure and protein homology with TOX2 revealed distinct methylation profiles by smoking status, histology, and cancer type." (PMID 22496870, 2012). "This study identified for the first time aberrant hypermethylation of the TOX2 promoter CpG island in cancer and characterized its potential contribution to carcinogenesis." (PMID 22496870, 2012). "In this study, a novel aberrantly hypermethylated CpG island in cancer was discovered within the TOX2 promoter." (PMID 22496870, 2012). "FNBP1, FRMD3, IGSF10, IL11RA, and TOX2 have known roles in cancer." (PMID 38398114, 2024). "Considering concerns about the potential lack of specificity when directly manipulating TET2 in CAR T cells and TET2’s role in cancer, we compared the tissue-specific expression levels of TET2, TOX, and TOX2." (PMID 37467321, 2023). "Tox and Tox2, are extensively studied in CD8+ T cells, in the context of chronic infections and cancer." (PMID 34548096, 2021). "This revealed a set of genes shared with human eTreg cells from affected sites in JIA, RA, and cancer including BATF, VDR, MICAL2, TOX2, KAT2B, PFKFB3, and IL12Rβ2." (PMID 33976194, 2021). "Moreover, we implicate several of these gene hits not only in ccRCC for the first time (BHLHB3, CAMK1, CDH13, ENPP3, KCNJ2, KSR1, PLOD2, and TCF8), but also in a cancer model for the first time (CEP290, EFCAB3, PGBD5, RAPGEF5, SSPN, and TOX2)." (PMID 24979721, 2014).
hematological malignancies (2 papers, 2021 to 2023). "Overall, TOX and TOX2 might be potential immune biomarkers and targets for hematological malignancy immunotherapy." (PMID 33743809, 2021). "In contrast, the role of TOX2 in hematological malignancies and solid tumors has not been established." (PMID 37032358, 2023).
infection (2 papers, 2021 to 2023). The state of being infected such as from the introduction of a foreign agent such as serum, vaccine, antigenic substance or organism. "As observed for the SRBC immunization model, Tox2-deficient mice displayed less cTFH cells in the blood at day 7 after primary infection with H3N2." (PMID 34623911, 2021). "The population of GC TFH cells decreased more rapidly in Tox2-deficient mice and became significantly lower at day 28 after infection as compared to WT mice." (PMID 34623911, 2021). "Serum levels of IFN-γ were relatively higher at day 7 after infection in Tox2-deficient mice than in WT mice." (PMID 34623911, 2021). "The frequencies of GC TFH cells in the mLNs were significantly lower at days 7 and 14 after infection in Tox2-deficient mice than in WT mice." (PMID 34623911, 2021). "Next, we examined whether Tox2-deficient mice can mount intact TFH cell response upon infection with an influenza virus." (PMID 34623911, 2021). "To examine whether the secondary TFH cell responses are also altered in Tox2-deficient mice, we challenged the mice by infection with the X-31 strain and then reinfected the mice 40 days later with an H1N1 influenza virus strain (A/Puerto Rico/8/34, PR8)." (PMID 34623911, 2021). "The frequency of GC TFH cells in Tox2-deficient CD4+ T cells was significantly lower in both mLNs and spleens at days 7, 14, and 28 after infection." (PMID 34623911, 2021). "Tox2-deficient mice displayed impaired secondary TFH cell expansion upon reimmunization with an antigen and upon secondary infection with a heterologous influenza virus." (PMID 34623911, 2021). "Similarly, there were increases in abundance after death of genes that are required for innate (Laao, Tox2) and adaptive immunity (Ms4a17, Usp18) and increased levels of the apoptotic genes (Fosb, Bcl2l11) that are normally activated by infection and injury." (PMID 36982814, 2023).
infectious disease (1 paper, 2023). A disorder directly resulting from the presence and activity of a microbial, viral, or parasitic agent in humans. "We also find evidence for selection at TOX2—a transcription factor that is essential for the development of T cells and natural killer cells, both of which are elevated in the Tsimane compared with post-industrial populations experiencing lower infectious disease burden." (PMID 36574663, 2023).
TOX2 also shares sentences with these, for which no sentence is quoted: neuroblastoma (2 papers); adenocarcinoma (1); atopic dermatitis (1); Autoimmunity (1); classic Hodgkin lymphoma (1); glioblastoma (1); melanoma (1); nephrolithiasis (1); NK/T-cell lymphomas (1); renal cell carcinoma (1); squamous cell carcinoma (1).